FBXW7 (F-box and WD repeat domain containing 7)
Diseases named in the same sentence as FBXW7 in open-access papers (continued):
Sharing a sentence is not in itself a finding about the gene and the disease.
cancer (continued). "Known cancer genes such as COL1A1 or STK11 were affected by duplications and other known genes such as CDKN2A, JAK2, PRDM1, FBXW7, or GOLGA5 were affected by deletions in several tumors of this subcluster." (PMID 32604718, 2020). "Given the ability of Fbxw7 to regulate NHEJ, inactivation of Fbxw7 promotes increased sensitivity of cancer cells to IR." (PMID 31632280, 2019). "Consistently, FBXW7 inactivation via genetic or pharmacological approach inhibits the NHEJ repair and sensitizes cancer cells to radiation." (PMID 31342282, 2019). "Two types of FBXW proteins have been found to regulate the EMT process in different types of human cancers, including the well-studied FBXW7 (also known as FBW7 and CDC4) and β-transducin repeat-containing protein (β-TrCP)." (PMID 30999935, 2019). "Among the CASEs, 26 events were identified to generate new isoforms in 22 cancer drivers, such as KRAS, SMARCA4 and FBXW7." (PMID 31695792, 2019). "In summary, FBXW7 and β-TrCP inhibit the EMT process via degradation of their substrates in human cancer cells." (PMID 30999935, 2019). "FBXW7 expression is down-regulated in non-small cell lung cancer (NSCLC) and patients with low FBXW7 expression have more aggressive cancer and a shorter survival time." (PMID 30086763, 2018). "A previous report showed that the interaction between HSF1 and Fbxw7 is diminished with HSF1 S303A and/or S307A mutants in cancer cells." (PMID 28194040, 2017). "Whereas, the functional roles of FBXW7 in EMT and cancer stem cell (CSC) characteristics of CCA is rarely reported, and the molecular pathways by which FBXW7 regulates EMT and CSC characteristics merit investigation." (PMID 25749036, 2015). "High performance of our resequencing approach is also illustrated by the fact that we identified mutations in known candidate drivers in T-ALL that were included in the collection of known cancer genes such as NOTCH1, FBXW7, PTEN, PHF6, WT1 and PIK3CA." (PMID 22675565, 2012). "FBXW7 is a component of the SCF (Skp1–Cullin–F-box) E3 ubiquitin ligase complex and can regulate cell proliferation, apoptosis, cell cycle, and differentiation in various human cancers by degrading proto-oncogenes." (PMID 41311387, 2025). "Previous reports combined with our results have confirmed that both FBXW7 and Wnt signaling pathways are involved in the stemness regulation of TNBC cells, but it remains unclear whether CHD4 also regulates cancer stem cells in TNBC." (PMID 38268032, 2024). "Collectively, these data suggested that FBXW7 is significantly downregulated in TNBC and might play a role as a cancer suppressor and favorable prognostic factor in TNBC patients." (PMID 38268032, 2024). "For example, both FBXW7 and TRIM28 were highly expressed in all cancer types." (PMID 37845222, 2023). "FBXW7 is a highly mutated gene in CRC, but its biological functions in cancer are not fully characterized." (PMID 37202390, 2023). "For example, the lack of FBXW7 in mice enhances cancer metastasis in both the cell-autonomous and the non-cell-autonomous ways." (PMID 36998461, 2023). "Although many studies have proposed FBXW7 as a therapeutic target for cancer, no suitable drug has entered clinical studies to date." (PMID 38027013, 2023). "On one hand, MYC is an FBXW7 target that stimulates mitochondrial biogenesis, and increased levels of MYC have been shown to correlate with increased resistance to certain cancer therapies." (PMID 35861150, 2022).
cancer (continued). "Thus, many kinases can negatively regulate FBXW7 stability by promoting its self-ubiquitination, which indicates a potential therapeutic strategy against MYC-driven cancer." (PMID 33494392, 2021). "Accordingly, these collective data highlight that losses or gains of FBXW7 (and perhaps other SCF complex member genes), may adversely contribute to cancer pathogenesis in a context-dependent manner." (PMID 35008511, 2021). "FBXW7 is capable of interacting with Mcl-1, the pro-survival Bcl-2 family member, to facilitate the degradation via ubiquitination in a GSK3 phosphorylation-dependent manner, leading to cancer cell apoptosis." (PMID 35006464, 2021). "To gain novel insight into cancer pathogenesis, we determined the prevalence of genetic and epigenetic alterations in six prototypic SCF complex member genes (SKP1, CUL1, RBX1, SKP2, FBXW7 and FBXO5) from patient datasets extracted from The Cancer Genome Atlas (TCGA)." (PMID 35008511, 2021). "Therefore, the FBXW7‐NOTCH axis has been a subject of intense study and research over the years, especially around the interactome's role in driving cancer development and progression." (PMID 33822486, 2021). "The major reason for this inconsistency is largely due to the disparity of cancer types, which could interfere with the function of c-JUN, FBXW7, and NICD1 and result in the apparently contradictory properties of MAGE-A1 in cancers." (PMID 31640756, 2019). "Thus, to further elucidate the physiological relevance of FBXW7/ZEB2 interaction, we used organoids (mini-gut), which are being used to model diseases including cancer." (PMID 30783098, 2019). "Further, deletion of FBXW7 in bone-marrow-derived stromal cells (BMSCs) resulted in the accumulation of Notch which consequently rendered elevation of chemokine (C-C motif) ligand 2 (CCL2), thereby promoting cancer metastasis in vivo." (PMID 30791487, 2019). "The level of circ-FBXW7 mRNA was sharply decreased after si RNA transfection, and it was remarkably improved after the overexpression by plasmid transfection in SW480 and SW620 cancer cell." (PMID 31519156, 2019). "Nuclear FBXW7 expression in cancer tissues tended to be lower than that in adjacent noncancerous tissues." (PMID 29348852, 2017). "Interestingly, in cancer cells phosphorylation of S303 and S307 by distinct protein kinases is required for the interaction of HSF1 with the Fbxw7 E3 ligase, responsible for ubiquitin-dependent degradation of nuclear HSF1 in melanoma cancer cells." (PMID 28194040, 2017). "However, to promote cancer activity, they also target different genes including C/EBPβ, FOXO1, NFI-A, STAT5A, ARTN, FBXW7, and SEPT6 (for miR-223) and FUS1, RhoC, PTEN, CDKN1A, TGFβR2, and NRF2 (for miR-93)." (PMID 26273679, 2015). "Specifically, the automated procedure was not able to map some well-known cancer genes, including cyclin-dependent kinase inhibitor 2A (CDKN2A), F-box and WD repeat domain containing 7 (FBXW7), and E2F transcription factor 3 (E2F3), to a hallmark." (PMID 26369414, 2015). "Nevertheless, our results demonstrating the identification of FBXW7 as a synthetic lethal target in the context of MCF10A-MYCER adds insight to the still enigmatic role of the interaction between FBXW7 and MYC in human cancer initiation, progression, and maintenance." (PMID 25669969, 2015). "In summary, this study shows that Fbxw7 expression is impaired in cancer tissues as compared with noncancerous tissues and that reduced Fbxw7 levels are correlated with poor clinicopathological features in HCC." (PMID 24884509, 2014). "Unlike all other targets of Fbxw7, Notch4 has not yet been investigated in human cancers though the protein is oncogenic when induced in the MMTV (mouse mammary tumor virus) mouse model." (PMID 17326833, 2007). "Additionally, the miR-223/FBXW7 axis orchestrates the epithelial-to-mesenchymal transition (EMT) process in colon cancer; this knowledge can be utilized in tailoring personalized anti-cancer treatments." (PMID 39125761, 2024).
cancer (continued). "Moreover, SLIs of FBXW7 are potential targets for cancer therapeutics in only some cancers as not all cancers have decreased expression of FBXW7." (PMID 31351478, 2019). "Mutations of FBXW7 and NOTCH1, which could lead to aberrant activation of Notch signaling pathway, were only detected in patients without germline cancer-associated variants." (PMID 30850667, 2019). "However, the clinical significance of Fbxw7 and the mechanisms involved in the anti-cancer effect of Fbxw7 in HCC are not clear." (PMID 24884509, 2014). "That is a strong possibility given that several oncogenes are regulated by FBXW7, including MYC, Notch, JUN and cyclin E. Thus, targeting different pathways in addition to the mTOR pathway might be necessary to effectively kill cancer cells in tumors driven by FBXW7 alterations." (PMID 24586741, 2014). "However, loss of FBXW7/hCDC4 expression in cancer can occur without genetic alteration, implicating a possible role for epigenetic silencing of FBXW7/hCDC4." (PMID 21122106, 2010). "Intriguingly, a latest research revealed that LSD1, often regarded as a demethylase of histone, directly bound to FBXW7 to disturb the formation of dimerization to facilitate autoubiquitination rather than activate the demethylation of FBXW7, which might offer a new target for cancer treatment." (PMID 35814468, 2022). "Here, we report a critical role of FBXW7 in the control of CCDC6 homeostasis in mitosis by regulating its ubiquitin-proteasomal degradation and providing evidences that the CCDC6 post-translational regulation in the cell cycle may account for differences in cancer cells drug response." (PMID 25885523, 2015). "Moreover, FBXW7 can ubiquitinate and degrade Eyes absent homolog 2 (EYA2), leading to increased immunogenicity of cancer cells, reduced carcinogenicity, and increased infiltration of natural killer (NK) cells and cytotoxic T cells." (PMID 39748950, 2024).
infection (22 papers, 2015 to 2025). The state of being infected such as from the introduction of a foreign agent such as serum, vaccine, antigenic substance or organism. "Recently, a genome-wide association study identified that FBXW7 was significantly downregulated in the chicken after infection with Salmonella pullorum, suggesting it may also play a role in controlling S. pullorum infection." (PMID 35651754, 2022). "FBXW7 mRNA was found to be increased in WT_Mm infected macrophages at 4 h and 8 h post infection (hpi), compared to MOCK and △PDIM cells, P < 0.01." (PMID 35651754, 2022). "We found that WT Mm strain infection increased FBXW7 expression in the tails of mice while △PDIM strain infection did not." (PMID 35651754, 2022). "In patients with mutation data, the factors significantly associated with death from infection versus all other deaths were 11q deletion (47/162 [29%] versus 40/209 [19%], P = 0.03) and mutations of the BRAF, FBXW7, NRAS and XPO1 genes." (PMID 33580200, 2021). "The FBXW7-deficient peritoneal macrophages expressed downregulated IFN-β and IFN-α4 mRNA upon infection with VSV, H1N1 virus or RSV and this phenomenon was also found in bone marrow-derived DCs (BMDCs) and bone marrow-derived macrophages (BMDMs)." (PMID 28287082, 2017). "Using zebrafish as the infection model to visualize the dynamics of these macrophages in the context of FBXW7 expression could contribute to understanding the role of FBXW7 on differentiation of macrophages." (PMID 35651754, 2022). "To investigate whether FBXW7 was regulated in WT_Mm-infected Raw264.7 macrophages, we infected Raw264.7 macrophages with WT_Mm, harvested the macrophages at various times post infection, and analyzed FBXW7 mRNA and protein levels." (PMID 35651754, 2022). "Therefore, we hypothesized that the NF-κB signaling pathway would be active when FBXW7 was upregulated during Mm infection." (PMID 35651754, 2022). "Among these patients, the FBXW7 mRNA was significantly lower in PBMCs from 20 cases of moderate infection in comparison with the 40 cases of mild infection, indicating that the expression of FBXW7 in PBMCs might have a correlation with the antiviral immunity of the host." (PMID 28287082, 2017). "To evaluate the effect of FBXW7 silencing on CRC cell lines, we established stably FBXW7 knocked-down CRC cell lines through infection of lentiviral particles expressing shRNAs." (PMID 31067777, 2019). "Consistently, deletion of FBXW7 in macrophages also led to decreased expression of ISG15 and ISG20 mRNAs after infection with VSV, H1N1 virus or RSV." (PMID 28287082, 2017). "In the univariate analysis in this subset of 400 patients, 11q deletion was significantly associated with death from infection versus deaths not due to infection, along with mutations of the BRAF, FBXW7, NRAS and XPO1 genes." (PMID 33580200, 2021). "Among the panel of 21 genes commonly mutated in CLL, univariate analysis showed that mutations of BRAF, FBXW7, NRAS and XPO1 were significantly associated with death from infection versus deaths not due to infection." (PMID 33580200, 2021).
adenocarcinoma (12 papers, 2013 to 2025). A common cancer characterized by the presence of malignant glandular cells. "FBXW7, which was found to be mutated in the adenocarcinoma, is a subunit of ubiquitin ligase (E3) and is involved in the cell cycle regulation." (PMID 23301059, 2013). "EBVaGCs with intestinal histology were frequently accompanied by genetic alterations, which were known to frequently occur in conventional intestinal-type adenocarcinoma, including KRAS, FBXW7, MUC6, ERBB2, CTNNB1, and ERBB2 amplification mutations." (PMID 37945587, 2023).
colon (3 papers, 2019 to 2025). "Importantly, our observations uncover a novel ubiquitination cascade composed of UBA6, UBE2Z, and FBXW7 that may regulate the degradation of the squamocin‐induced EZH2/MYC axis in pan‐gastrointestinal tumors." (PMID 39823459, 2025).
hematologic malignancies (3 papers, 2012 to 2022). "Conversely, activation of NOTCH1 signaling through gain-of-function mutations in NOTCH1, first described in T-ALL, or loss-of-function mutations in NOTCH1 regulators, such as FBXW7 and NUMB, has been linked to therapeutic recalcitrance of hematologic malignancies." (PMID 22768113, 2012). "FBXW7 is the most important E3 ligase for MYC ubiquitination and proteasomal degradation in hematologic malignancies, which is dependent on T58 phosphorylation of MYC41,48." (PMID 33298911, 2020).
hematological cancer (3 papers, 2015 to 2023). "In NSCLC cells with loss of FBXW7, treatment with Entinostat, a class 1 HDAC inhibitor, effectively overcame Taxol resistance and may be beneficial in treating aggressive Taxol-resistant NSCLCs and hematological cancer cells that lack expression of FBXW7." (PMID 37408248, 2023). "T-cell acute lymphoblastic leukemia (T-ALL) is the only hematological tumor that can be caused by the deletion of FBXW7 without the necessity of other cancer-promoting elements." (PMID 32674429, 2020).
neurodevelopmental disorder (3 papers, 2021 to 2025). A behavioral and cognitive disorder with onset during the developmental period that involves impaired or aberrant development of intellectual, motor, or social functions. "It is undoubted that FBXW7 and its substrates function in different vital neurodevelopmental processes, but the potential roles of FBXW7 in the pathogenesis of neurodevelopmental disorders still remain to be investigated." (PMID 34512273, 2021). "There is no FBXW7 mutation identified to be associated with any neurodevelopmental disorders at present, however, functional implications or mutations of its substrate have been widely reported in relevant diseases." (PMID 34512273, 2021). "Additionally, potential therapeutic effect on neurodevelopmental disorders treatment via targeting FBXW7 or its substrates is also discussed." (PMID 34512273, 2021). "Considering functional implications of FBXW7 in neurodevelopment, it may be beneficial to explore effective methods via targeting FBXW7 or its substrate for treatment of neurodevelopmental disorders." (PMID 34512273, 2021).
cardiovascular diseases (2 papers, 2012 to 2017). "As our findings show that Fbxw7 deficiency can lead to the accumulation of NICD in endothelial cells, it appears worthwhile to investigate whether mutations in the Fbxw7 gene are linked to human cardiovascular diseases." (PMID 22848434, 2012). "However, the relationship between the FBXW7 gene and cardiovascular diseases has not yet been studied." (PMID 29152152, 2017).
neurodegenerative disease (2 papers, 2024 to 2025). A disorder of the central nervous system characterized by gradual and progressive loss of neural tissue and neurologic function. "Among them, the role of FBXW7 has been mentioned in neuronal disease, but the exact role of FBXW7 in this process (DDR of neurodegenerative diseases) remains largely understudied." (PMID 41184269, 2025).
FBXW7 also shares sentences with these, for which no sentence is quoted: breast (4 papers); kidney cancer (4); Alzheimer disease (2); Burkitt lymphoma (2); diabetic retinopathy (2); ductal adenocarcinoma of the pancreas (2); endometrial tumors (2); endometriosis (2); Hepatic steatosis (2); HIV-1 infection (2); Hodgkins lymphoma (2); Parkinson disease (2); salivary gland neoplasm (2); small cell lung carcinoma (2); urothelial carcinoma (2); alcoholism (1); ampullary cancer (1); amyotrophic lateral sclerosis (1); anaplastic large cell lymphoma (1); anemia (1); Anxiety (1); apocrine carcinoma (1); arteriosclerosis (1); Arthritis (1); Atrophy (1); autoimmune disease (1); bacterial infection (1); blood disease (1); breast invasive ductal carcinoma (1); carcinoid (1).
A further 75 diseases each share a sentence with FBXW7 in 1 paper.